NLRP6 (NLR family pyrin domain containing 6)
Diseases named in the same sentence as NLRP6 in open-access papers (continued):
Sharing a sentence is not in itself a finding about the gene and the disease.
infection (continued). "Similarly, NLRP6 KO mice demonstrated decreased cell death through pyroptosis and necroptosis following infection." (PMID 30248149, 2018). "In addition, NLRP6 KO mice displayed increased neutrophil recruitment following infection, and when neutrophils were depleted the protective effect was lost." (PMID 30248149, 2018). "The recently described regulator NLRP6 has been demonstrated to be involved in the regulation of faecal microbiota and has been demonstrated to regulate and influence goblet cell proliferation and mucin secretions which are observed following infection." (PMID 25938477, 2015). "In addition, it would be interesting to establish to what extent NLRP6-dependent sensing of endolysosomal stability may be relevant beyond the intestine/infection contexts, but this will require similarly strict delineation (as presented here) from NLRP3." (PMID 41266654, 2026). "Finally, we assayed cytokine secretion in HIEC-6 cells expressing NLRP6 and found that infection with wild-type L. monocytogenes elicited increased IL-1β secretion, while the levels of IL-1β release upon infection with Δhly L. monocytogenes were comparable to uninfected controls." (PMID 41266655, 2026). "We also assessed whether Nlrp6 impacted infection-induced IL-18 and IL-22 release." (PMID 39428744, 2024). "Similarly, NLRP6 serves as a negative regulator during infection with Staphylococcus aureus." (PMID 36761775, 2023). "However, Nlrp6−/− mice had more bacteria in the lungs after infection compared with WT mice." (PMID 36224650, 2022). "However, NLRP3- or NLRP6-deficiency did not compromise the ability of mice to survive an i.n. infection with F. tularensis LVS." (PMID 27779193, 2016). "Levels of NLRP6 have been inversely correlated to the levels of Prevotellaceace in the gut, thus increased NLRP6 expression resulting in the changes in the mucin secretion that we see during infection, may be a factor in the reduction of Prevotella that we identified." (PMID 25938477, 2015). "All these cell types are exposed to infection by pathogens, but the different expression profiles of NLRP3, NLRP6, NLRP10, and NLRP12 probably reflects that each cell type has a distinct cell physiology that pathogens would evolve to target." (PMID 39076995, 2024). "Ligand stimulation, such as infection with rotavirus or murine hepatitis virus A59, promotes liquid–liquid phase separation (LLPS) of NLRP6." (PMID 37515138, 2023). "The inflammasome molecules AIM2, NLRP3, NLRP6 and NLR Family Apoptosis Inhibitory Protein (NAIP)/NLRC4 were reported to play important roles in epithelial cells by protecting against infection and maintaining tissue homoeostasis." (PMID 37365163, 2023). "In this review, we will focus on the NLRP3, NLRP6, NLRC4 and AIM2 inflammasomes and how they are activated and regulated during infections with Gram-positive bacteria, including Staphylococcus spp., Streptococcus spp." (PMID 36761775, 2023). "However, NLRP6 might exhibit detrimental functions in other infection settings." (PMID 38146368, 2023). "T. gondii infection time-dependently induced NLRP3 and ASC protein expression, adequately induced NLRP6 and cleaved caspase-1 expression, and moderately induced NLRC4 expression at 4 h post-infection." (PMID 33712075, 2021). "Upon infection of mouse or human macrophages, L. monocytogenes can be detected by multiple inflammasomes, including AIM2, NLRC4, NLRP3, NLRP6, caspase‐11 and NLRP1B." (PMID 32185892, 2020). "UPEC significantly decreased the gene expression of CASP4, NLRP1, NLRC4, NLRP6 and AIM2 at MOI 1 and MOI 10 after 3 h of infection compared to unstimulated cells." (PMID 33318544, 2020). "Cells were harvested at 2, 8, and 24 h post-infection and the level of expression of NLRP3, NLRP6, NLRP12, IFI16, and AIM2 was determined by western blot." (PMID 31367214, 2019).
infection (continued). "To determine whether the detrimental effects of NLRP6 are bacterial strain specific, we infected WT and KO mice with a methicillin-susceptible Staphylococcus aureus strain (MSSA, Newman strain) and measured the bacterial burden in lungs and BALF at 24-hours post-infection." (PMID 30248149, 2018). "In NLRP6 knockout mouse studies, animals lacking NLRP6 deteriorated more rapidly compared to the wild‐type counterparts following infection with MNV, and this was found to be independent of the gut microbiome composition." (PMID 39878363, 2025). "We found that both NLRP6 and NLRP9b were induced in primary IECs from mouse intestine organoids of Trim29fl/fl mice after infection of EMCV or Rotavirus, further confirming that NLRP6 and NLRP9b are one of ISG and the degradation of NLRP6 and NLRP9b are mediated by TRIM29." (PMID 39396665, 2025). "In addition, the reduction of NLRP6 and NLRP9b expression and upregulation of TRIM29 were first observed on 1 h in primary IECs from mouse intestine organoids of Trim29fl/fl mice after infection of EMCV or Rotavirus." (PMID 39396665, 2025). "In response to infection with Listeria monocytogenes, Salmonella enterica serovar Typhimurium (S. Typhimurium) or Escherichia coli, WT mice and mice lacking NLRP6 have similar levels of caspase‐1 activation and IL‐1β release." (PMID 39351983, 2025). "Other studies have shown a reduction in caspase‐1 activation and IL‐1β secretion in bone‐marrow‐derived macrophage (BMDMs) lacking NLRP6 compared to WT BMDMs following infection with Staphylococcus aureus or L. monocytogenes." (PMID 39351983, 2025). "Unlike the Casp1/11−/− mice however, Nlrp6−/− mice phenocopied their WT littermates in terms of infection-induced cecal pathology, with both groups displaying severely disrupted epithelial integrity, IEC sloughing and immune cell infiltration." (PMID 39428744, 2024). "Mice lacking NLRP6 were highly resistant to infection with a variety of bacterial pathogens, such as Salmonella typhimurium, Listeria monocytogenes and Escherichia coli." (PMID 36920176, 2023). "Studies have shown that NLRP6 and NLRP12 can act as a negative regulator of the NF-κB and mitogen-activated protein kinase (MAPK) signal pathways to attenuate intestinal inflammation during the infection of K. pneumoniae." (PMID 36506034, 2022). "It was possible to observe that the lack of NLRP6 was important in the model of Brucella infection, but only when the infection was administered via oral route, not through the intraperitoneal administration." (PMID 33617596, 2021). "NLRP6, a member of the nucleotide‐binding domain, leucine‐rich repeat‐containing (NLR) innate immune receptor family, participates in the progression of intestinal inflammation and enteric pathogen infections." (PMID 30515917, 2019). "To investigate whether NLRP6 triggers inflammasome activation during S. aureus infection, we infected BMDMs from WT and NLRP6 KO (KO) mice with S. aureus (MOI: 20) and measured the extent of caspase-1 activation at 8 hours post-infection." (PMID 30248149, 2018). "By contrast, anti-TRIM29 Ab could not pull down NLRP6 or NLRP9b without infection, suggesting there were indeed interactions of TRIM29 with NLRP6 and NLRP9b in primary IECs from mouse intestine organoids under the condition of enteric RNA virus infection." (PMID 39396665, 2025). "However, there was no obvious ubiquitination of NLRP6 and NLRP9b in mouse IECs from Trim29fl/fl and Trim29IEC-KO mice without infection." (PMID 39396665, 2025). "To determine whether NLRP6 engages in the regulation of SARS-CoV-2 immunity in IECs, we established NLRP6 knockout cell line in basis of Caco-2-ACE2-N IECs and evaluated the cytokine production with SARS-CoV-2 GFP/ΔN-trVLP infection." (PMID 36825215, 2022). "Interestingly, in the absence of infection, the Nlrp6-/- animals demonstrated to have higher levels of sIgA in relation to WT animals." (PMID 33617596, 2021).
infection (continued). "Real-time reverse transcription-PCR (RT-PCR) results showed that the expression of IL-1β mRNA was significantly induced in S. pneumoniae-infected macrophages of WT and NLRP6−/− mice at 9 h post infection, indicating that NLRP6 did not affect S. pneumoniae-induced IL-1β transcription." (PMID 33918100, 2021). "Moreover, it remains unknown whether the NLRP6 inflammasome is activated by microbial infections and whether NLRP6 co-localizes with ASC and caspase-1 during such infections to induce pyroptosis." (PMID 30248149, 2018). "Finally, the finding that NLRP6 is not just a sensor for pathogen infection, but a general sensor for perturbed homeostasis of the endolysosomal system could potentially link NLRP6 to a plethora of different pathological processes." (PMID 41266655, 2026). "Likewise, while miR-650 is thought to promote NLRP6 inflammasome-related apoptosis, NLRP6 itself acts as an auto-inhibitor by decreasing the apoptosis increased by the effect of miR-650 through a direct binding of the Nlrp6 3’UTR and miR-650, to restore cell homeostasis after infection clearance." (PMID 38644450, 2024). "However, the expression of p-p65 and p-IκBα was significantly higher in S. pneumoniae-infected NLRP6−/− macrophages compared with WT macrophages (* p < 0.05) while the expression of p-ERK1/2 was only markedly increased in NLRP6−/− macrophages at 15 min and 30 min post infection." (PMID 33918100, 2021). "How NLRP6 can form an inflammasome complex but also inhibit NF-κB and ERK in the same cell during the same infection is not known." (PMID 41062723, 2025). "We thus treated Listeria-infected, NLRP6-expressing GFP-ASCtg cells with the bacteriostatic antibiotics tetracycline and chloramphenicol 45 min after infection to allow primary escape from the invasion vacuole, but not continuation of the life cycle in the cytosol." (PMID 41266655, 2026).
tumor (48 papers, 2013 to 2025). "For instance, AURKA was consistently associated with poor prognosis, while NLRP6 appeared protective in most tumour types." (PMID 40696496, 2025). "To further explore the potential role of elevated ZBP1 and NLRP6 expression in oHSV infection in tumor cells, we generated ZBP1-deficient 4T1 and 4MOSC1 cells, as well as NLRP6-deficient 4T1 and 4MOSC1 cells, using CRISPR/Cas9-based gene editing." (PMID 38693119, 2024). "The relationship between NLRP6 expression and clinical features of LIHC was investigated, and the findings revealed that NLRP6 expression was significantly associated with age, race, tumor grade, AFP level, and OS event." (PMID 35651286, 2023). "This high expression of NLRP6 has been associated with a higher survival rate, which suggests that NLRP6 plays a beneficial role as a tumor-suppressing gene in NHSCC77." (PMID 35650327, 2022). "High levels of CD206 were associated with metastasis and higher NLRP6 expression in the tumor stroma." (PMID 36270983, 2022). "A significant increase in tumor number and burden was observed in NLRP6-deficient mice compared to wild-type controls after chemical induction." (PMID 27206676, 2016). "Additionally, high NLRP6 expression has been associated with more abundant neutrophils, NK cells, DC cells, and other tumor‐antagonizing immune cells." (PMID 35651286, 2023). "NLRP6 is tightly linked to intestinal flora and inflammation, and it plays a role in tumorigenesis by influencing the tumor's inflammatory response, immunological microenvironment, and tumor cell characteristics." (PMID 37415625, 2023). "In intestinal epithelial cells, the NLRP6 inflammasome is suggested to play a critical role in regulating gut microbiome composition, goblet cell function and related susceptibility to gastrointestinal inflammatory, infectious and neoplastic diseases." (PMID 36270983, 2022). "In conclusion, these NLRP6 dependent pyroptosis-related lncRNAs might provide new insights into the mechanisms underlying tumorigenesis and anti-tumor immunity." (PMID 35308537, 2022). "However, earlier studies have also implicated, for example, ASC, NAIPs, NLRP3 and NLRP6 as tumour suppressors." (PMID 32068945, 2020). "AIM2, CASP3, NLRC4, TNF, and NLRP6 may be associated with tumour drug resistance." (PMID 35246158, 2022). "Hence, the loss of NLRP6 or IL-18 in epithelial tumor cells was associated to metastatic progression and epithelial expression of inflammasome components had a more important impact on tumor evolution." (PMID 33255437, 2020). "In the Hepa 1-6 syngeneic mouse model, in which mice were pretreated with antibiotics, C. albicans gavage resulted in greater tumor burden and induction of Nlrp6 expression compared with control mice administered PBS59." (PMID 41087644, 2025). "The correlation between tumor progression and epithelial expression of NLRP6 and IL18 establishes NLRP6 and IL18 expression levels in sporadic CRC cells as robust predictors of patient outcomes." (PMID 38892354, 2024). "Compared with normal tissues, BAK1 and GSDME levels were markedly elevated in HCC tumor tissues, meanwhile, the expression of the NLRP6 showed the opposite trend as decreasing in HCC tumor samples in contrast with normal samples." (PMID 37149620, 2023). "To comprehensively understand the role of NLRP6 in tumour progression, we investigated the biological function of NLRP6." (PMID 37770465, 2023). "People pay more and more attention to the relationship between NLRP6 and different types of tumors, but the specific function of NLRP6 in tumor formation, development, and invasion is still controversial." (PMID 37415625, 2023). "The different effects of NLRP6 on tumour growth depend on tissue specificity, the tumour microenvironment, and, most importantly, the molecules with which NLRP6 directly interacts under specific physiological conditions." (PMID 37770465, 2023).
tumor (continued). "Collectively, our results suggest that NLRP6 promotes p85α degradation via selective autophagy to drive tumorigenesis, and the interaction between NLRP6 and p85α can be a promising therapeutic target for tumour treatment." (PMID 37770465, 2023). "We currently need to define the role of NLRP6 in the occurrence and progression of HCC and comprehend the magnitude of NLRP6's transition between tumor inhibition and cancer promotion." (PMID 37415625, 2023). "We demonstrated that NLRP6 promoted tumour growth through its direct interaction with p85α to promote p85α degradation." (PMID 37770465, 2023). "Due to the high similarity between NLRP6 and NLRP3, it is believed that the relationship between NLRP6 and tumor will be as clear as NLRP3 in the future." (PMID 37415625, 2023). "Since Nlrp6−/− mice mimic these hallmarks of intestinal dysbiosis, we used these mice as a tool to investigate how intestinal dysbiosis orchestrates the tumor microenvironment and affects the anti-tumor response during steatohepatitis progression." (PMID 35803930, 2022). "Taken together, we suggest that lncRNAs included in our prognosis model participate in tumor development by regulating the NLRP6-dependent pyroptosis pathway." (PMID 35308537, 2022). "NLRP6 expressed in Ly6Chi monocytes and neutrophils in the intestinal lamina propria controls tumor growth in the inflamed intestine via the production of IL-1851." (PMID 35650327, 2022). "The effect of epithelial IL-18 downregulation seemed to be stronger on tumor evolution than epithelial NLRP6." (PMID 33255437, 2020). "In the AOM-DSS CAC model, Nlrp6−/− mice had increased pathology and tumor numbers compared to wild-type mice." (PMID 24273542, 2013). "Further studies of NLRP6 will need to be pursued to determine if it contributes to tumor progression or protection." (PMID 24273542, 2013). "Thus, interrupting the interaction between NLRP6 and p85α appears to be an attractive strategy to inhibit tumour growth." (PMID 37770465, 2023). "We also found a novel potential tumor suppressor gene NLRP6, which may negatively regulate the E2F and MYC pathways and be associated with higher immune cell infiltration levels, which lead to better prognosis." (PMID 35651286, 2023). "Our work also provides evidence that disrupting the NLRP6/p85α interaction to inhibit the PI3K/AKT pathway might be an effective therapeutic strategy against tumours." (PMID 37770465, 2023). "The NLRP6-p85α interaction offers a potential therapeutic target for tumor treatment." (PMID 37770465, 2023). "Therapeutic methods to regulate intestine microecology are a novel direction for tumor treatment, and studying NLRP6 modulation in combination with modifying intestinal microecological agents may open up new avenues for this therapeutic approach." (PMID 37415625, 2023). "It has been discovered that NLRP6 functions as a tumor suppressor in GC." (PMID 37415625, 2023). "In conclusion, NLRP6-dependent pyroptosis-related lncRNAs play important roles in tumor immunity and may be potential predictors and therapeutic targets for HCC." (PMID 35308537, 2022). "Therefore, we concluded that NF-κB is a critical downstream factor of NLRP6 in SCLC tumor-derived exosome-induced MØ polarization." (PMID 36270983, 2022). "In addition, our results showed that NLRP6 is downregulated in tumor tissues at the transcriptional and translational levels, and patients with higher expression levels of NLRP6 had longer OS." (PMID 35308537, 2022). "In addition, other members such as NLRP6 have also been shown to exhibit an anti-tumor role through the suppression of the expression of pro-inflammatory cytokines in the tumor microenvironment." (PMID 35203462, 2022). "Reprogramm tumor cell metabolism and contributes to the cancer progression dependent on NLRP6." (PMID 36246294, 2022). "We hypothesized that Nlrp6−/−-mediated intestinal dysbiosis aggravates steatohepatitis and increases tumor burden in NEMO∆hepa mice." (PMID 35803930, 2022).